TRIAP1 (TP53 regulated inhibitor of apoptosis 1)
Diseases named in the same sentence as TRIAP1 in open-access papers (continued):
Sharing a sentence is not in itself a finding about the gene and the disease.
cancer (16 papers, 2008 to 2025). A tumor composed of atypical neoplastic, often pleomorphic cells that invade other tissues. "In TCGA data, high expression of TRIAP1 was a high‐risk factor for cancer patient survival, and it was significantly associated with poorer OS in 7 tumors and poorer disease‐specific survival (DSS) in eight tumors (hazard ratio (HR) > 1 and p < 0.05)." (PMID 37256211, 2023). "Similar to yeast, TRIAP1 loss in human cancer cells led to the appearance of abnormal mitochondrial morphology." (PMID 36387192, 2022). "The underlying mechanism by which fibroblast-derived TRIAP1 is secreted and subsequently taken up by adjacent cancer cells and/or shuttled between the stromal and the tumour cells needs to be investigated further." (PMID 30871022, 2019). "However, additional experimental evidence is required to establish the presence of a functional cytoplasmic-reduced molten globule state of TRIAP1 in the context of both normal physiological conditions and cancer-associated contexts." (PMID 39909379, 2025). "Likewise, in most cancers, high expression of TRIAP1 is a high‐risk factor for patient prognosis." (PMID 37256211, 2023). "Results revealed that circRNA NFIX silencing repressed the growth of cancer cells and induced cell apoptosis by upregulating miR‐214‐3p and inhibiting TRIAP1 expression, which was a potential biomarker for NSCLC." (PMID 39135128, 2024). "Numerous studies consistently demonstrate high expression levels of TRIAP1 in tumor cells, thereby facilitating the progression of various malignant tumors." (PMID 38769122, 2024). "Experiments have shown that the expression level of TRIAP1 is generally elevated in 9 types of cancers." (PMID 37256211, 2023). "The expression level of TRIAP1 in cancer was significantly inversely correlated with ESTIMATE scores and positively correlated with CAFs activation status and tumor stemness." (PMID 37256211, 2023). "In OC, overexpressed TRIAP1 inhibits apoptosis of cancer cell SKOV3 by inhibiting the activation of APAF1/apoptosome." (PMID 37256211, 2023). "Overexpressed miR‐539370 and miR‐1301377 can suppress the malignant phenotype of SaOS cell lines and promote cancer cell apoptosis by targeting TRIAP1." (PMID 37256211, 2023). "TRIAP1 plays an important role in the occurrence and development of cancer by inhibiting the apoptosis of cancer cells." (PMID 37256211, 2023). "Overexpressed miR‐203 can target and inhibit TRIAP1, thereby promoting apoptosis of cancer cells (RasB1)." (PMID 37256211, 2023). "TRIAP1 can promote the resistance of cancer cells to radiation and various anticancer drugs, including DOX, DDP, tyrosine kinase inhibitor (TKI), TAM, and taxol (PTX)." (PMID 37256211, 2023). "Many studies have so far confirmed that TRIAP1 is highly expressed in cancers of various human systems and plays a role in promoting cancer." (PMID 37256211, 2023). "In TC, the highly expressed MFI2‐AS1 upregulated the expression level of TRIAP1 by competitively inhibiting miR‐125a‐5p, inhibited the apoptosis of cancer cells, and promoted the proliferation, invasion, and metastasis of cancer cells." (PMID 37256211, 2023). "Overexpressed miR‐18a targets and inhibits TRIAP1, thereby inhibiting the cell cycle and proliferation of cancer cells (A2780cp and A2780s) and promoting cancer cell apoptosis." (PMID 37256211, 2023). "TRIAP1 expression was significantly higher in multiple drug‐resistant cancer cell lines (doxorubicin (DOX), cisplatin (DDP), tamoxifen (TAM), and etoposide (VP‐16)) than in corresponding drug‐sensitive cell lines." (PMID 37256211, 2023).
cancer (continued). "In SaOS, highly expressed circPVT1 upregulates the expression level of TRIAP1 by competitively inhibiting miR‐137 and hinders the apoptosis of cancer cells (KHOS and U2OS), ultimately promoting the malignant progression of cancer." (PMID 37256211, 2023). "TRIAP1 is more expressed in multidrug‐resistant cancer cell lines (DOX, DDP, TAM, and VP‐16) than in corresponding sensitive cell lines." (PMID 37256211, 2023). "Deciphering the molecular regulation and function of TRIAP1 is crucial for the understanding of the advantage that its expression provides to cancer cells." (PMID 36387192, 2022). "TRIAP1 was reported to protect cancer cells from apoptosis through interaction with HSP70 or the repression of cyclin-dependent kinase inhibitor 1 (p21)." (PMID 35955492, 2022). "It is therefore critical to understand the metabolic and proliferative advantages that TRIAP1 expression provides to cancer cells." (PMID 36387192, 2022). "Taken together, in vitro and in vivo findings indicate that the expression of the mitochondrial protein TRIAP1 provides a growth advantage to HCT116 cancer cells." (PMID 36387192, 2022). "Although recent reports indicate that TRIAP1 is a prosurvival factor abnormally overexpressed in various types of cancer, knowledge about its molecular and metabolic function in human cells is still elusive." (PMID 36387192, 2022). "We have identified apoptosis inhibitor TRIAP1 as a stromal-derived factor with the potential to induce cancer cell resistance." (PMID 30871022, 2019). "Furthermore, it provides a possible explanation for the correlation between elevated TRIAP1 levels and drug resistance, as cancer cells often develop resistance to therapeutic interventions through apoptosis evasion." (PMID 39909379, 2025). "Elucidating the reason why TRIAP1 is different in PCPG from most other cancers may lead to a new understanding of TRIAP1 function." (PMID 37256211, 2023). "TRIAP1 is abnormally highly expressed in a variety of tumors and has a cancer‐promoting effect." (PMID 37256211, 2023). "When TRIAP1 expression is inhibited, the malignant phenotype of cancer cells is also inhibited." (PMID 37256211, 2023). "In order to better understand growth inhibitory and metabolic impacts of TRIAP1 knockdown on HCT116 cancer cells, we performed transcriptomic analysis of isogenic HCT116 cells transduced with control (Ctrl #1 and #2) or TRIAP1 (TRIAP1 #1, #2, and #3) shRNAs and grown under standard conditions." (PMID 36387192, 2022). "High levels of TRIAP1 were reported in various types of cancer." (PMID 36387192, 2022). "The level of TRIAP1 mRNA was detected in human tissues, and the results showed that this gene is also up-regulated in a variety of malignant tumors, and it plays a role in promoting cancer in most tumors." (PMID 35480301, 2022). "Hence, it could be that “aberrant” MAMs in cancer cells or abnormal expression of TRIAP1/PRELI would modulate cardiolipin levels and cytochrome c release, and thus cell susceptibility to apoptosis that can be exploited for cancer therapy." (PMID 32039198, 2019).
cancer (continued). "When TRIAP1 is overexpressed, it can impede the activation of APAF1/apoptosome, consequently blocking apoptosis in cancer cells." (PMID 38003971, 2023). "PeCa patients overexpressing TRIAP1 have higher tumor histological grades and shorter local RFS and thus can be used as a predictor of cancer recurrence." (PMID 37256211, 2023). "In BrC, highly expressed miR‐107 targets TRIAP1 in the BrC cell line (MCF‐7), leading to down‐regulation of cancer cell MCF‐7 viability and promoting cancer cell apoptosis." (PMID 37256211, 2023). "In NPC, overexpressed miR‐320b targets and inhibits TRIAP1, promotes mitochondrial fragmentation and Cyt c release, which in turn inhibits the proliferation of cancer cells (CNE‐2 and SUNE‐1) and promotes cancer cell apoptosis." (PMID 37256211, 2023). "TRIAP1 is highly expressed in MM,371 and overexpressed TRIAP1 can inhibit the activation of APAF1/apoptosome, thereby inhibiting cancer cell apoptosis, leading to cancer progression." (PMID 37256211, 2023). "We first checked the impact of TRIAP1 knockdown (shRNAs TRIAP1 #1, #2, #3) on the mitochondrial ultrastructure in human HCT116 cancer cells, by performing transmission electron microscopy (TEM)." (PMID 36387192, 2022). "The rationale was that, similar to many cancer cells, HCT116 cells rely on glutamine for survival and that one of the most significant metabolic pathways enriched in relation with TRIAP1 depletion in HCT116 cells was glutamine/glutamate metabolism." (PMID 36387192, 2022). "Our results are in agreement with this possibility, since the knockdown of TRIAP1 in colorectal HCT116 cancer cells does not lower CL levels and has no significant impact on mitochondrial functions that could reflect a perturbation in CL production." (PMID 36387192, 2022). "TRIAP1 could bind to HSP70 in the cytoplasm and inhibit the formation of apoptosomes and caspase-9 activation, and had been shown to be upregulated in many types of cancers." (PMID 35109849, 2022).
tumor (11 papers, 2008 to 2025). "Further on, TRIAP1-expressing stromal fibroblasts mediate radiation resistance in vivo when respective cells are co-implanted with CAV1-deficient PC3 tumour cells." (PMID 30871022, 2019). "Numerous studies have shown that TRIAP1 is a novel tumor diagnostic and prognostic marker." (PMID 37256211, 2023). "Previous studies have suggested that TRIAP1 functions as a tumor-promoting gene, whereas LC3B acts as a tumor suppressor gene." (PMID 38769122, 2024). "Meanwhile, low expression of TRIAP1 inhibited tumor growth and metastasis in xenografted male nude mice." (PMID 37256211, 2023). "Meanwhile, low expression of TRIAP1 can also inhibit tumor growth and metastasis in xenografted BALB/nude mice." (PMID 37256211, 2023). "In summary, the results of this study show that miR-107 is lowly expressed as a tumor suppressor gene in GC, and TRIAP1 is highly expressed as an oncogene in GC." (PMID 35480301, 2022). "HCT116 cells transduced with either control (Ctrl) or two distinct TRIAP1 (TRIAP1 #1 and #3) shRNAs were injected subcutaneously into the flank of nude mice, and tumor growth was monitored as previously indicated." (PMID 36387192, 2022). "Here, we report that the expression of TRIAP1 supports the in vitro proliferation and in vivo tumor growth of human colorectal HCT116 cancer cells." (PMID 36387192, 2022). "To further demonstrate the tumour suppressor function of miR-539 through targeting TRIAP1, we overexpressed TRIAP1 for 143b and MG63 cells in the miR-539 mimic group, and we named this group as group “mimic + TRIAP1”." (PMID 33879126, 2021). "In other words, overexpression of TRIAP1 counterbalanced the tumour suppressor effect of the miR-539 mimics on cell proliferation in 143B and MG63 cells." (PMID 33879126, 2021). "TRIAP1 expression in prostate epithelial cells increased with higher Gleason scores, that is, lower tumour differentiation." (PMID 30871022, 2019). "To mimic the human situation we performed subcutaneous transplantations onto the hind limb of NMRI nude mice by injecting CAV1-silenced PC3(-) tumour cells in combination with control-transfected or TRIAP1-GFP-expressing WPMY-1 prostate fibroblasts." (PMID 30871022, 2019). "The tumour growth delay after radiation was significantly decreased in PC3(-)-derived tumours co-implanted with TRIAP1-expressing WPMY-1." (PMID 30871022, 2019). "Conversely, tumor growth, tumor size and tumor weight were significantly inhibited by TRIAP1 knockdown (P < 0.05)." (PMID 27428374, 2016). "TRIAP1 overexpression significantly enhanced tumor growth, with regard to both tumor volume and tumor weight, compared with the control LV-Vector group." (PMID 27428374, 2016). "All together, these results support that TRIAP1 promotes NPC tumor growth and inhibits cell apoptosis in vivo." (PMID 27428374, 2016). "In conclusion, our study revealed TRIAP1 as an oncogene in tumor progression and unfavorable survival, and miR-320b as a novel post-transcriptional regulator of TRIAP1 expression in NPC." (PMID 27428374, 2016). "The proteomic analyses revealed that the combination treatment significantly downregulated tumour-promoting genes such as HLA-F, TRIAP1, TMBIM6, and ENTPD8, suggesting reduced mitochondrial integrity and immune escape, thereby enhancing apoptotic susceptibility." (PMID 41516237, 2025). "TRIAP1 plays an important role in promoting tumor resistance to treatment." (PMID 37256211, 2023). "We also calculated the correlation of TRIAP1 with the tumor microenvironment and tumor stemness." (PMID 37256211, 2023). "Meanwhile, the circPVT1/miR‐137/TRIAP1 axis promoted tumor growth in xenografted BALB/c nude mice." (PMID 37256211, 2023). "Similarly, low expression of TRIAP1 inhibited tumor progression in NCI‐N87 cell xenograft in BALB/c athymic nude mice." (PMID 37256211, 2023). "Meanwhile, low expression of TRIAP1 inhibited tumor growth in xenografted BALB/c nude mice." (PMID 37256211, 2023).
tumor (continued). "Low activity of antitumor immune cells, high activity of CAFs, and high tumor stemness may be the reasons for malignant tumor progression and poor prognosis in patients with high TRIAP1 expression." (PMID 37256211, 2023). "In addition, dual luciferase reporter gene and rescue experiments confirmed that miR-107 exerts tumor suppressor activity on GC cells NCI-N87 by targeting TRIAP1." (PMID 35480301, 2022). "Also, western blot results proved that the TRIAP1 protein level was remarkably lower in tumor tissues from the sh-circ group than the sh-NC group." (PMID 33981772, 2021). "High expression of TRIAP1 in tumours often indicates poor prognosis for patients." (PMID 33879126, 2021). "Furthermore, RT-qPCR assays indicated that the levels of circPVT1 and TRIAP1 were declined in tumor tissues from sh-circ-transfected KHOS/DXR cells, whereas the miR-137 level was enhanced." (PMID 33981772, 2021). "Next, we asked whether fibroblastic tumour stroma-derived TRIAP1 accounts for an increased radiation resistance in PC3 xenograft tumours." (PMID 30871022, 2019). "Next, we investigated the effect of TRIAP1 on tumorigenesis in vivo through xenograft tumor models." (PMID 27428374, 2016). "TRIAP1 is the homolog of yeast mitochondrial intermembrane protein MDM35, which can play a tumor‐promoting role by blocking the mitochondria‐dependent apoptosis pathway." (PMID 37256211, 2023). "In PCPG, the TRIAP1 expression level was significantly positively correlated with ESTIMATE scores, and significantly negatively correlated with tumor stemness." (PMID 37256211, 2023). "For this purpose, control (pCtrl) or TRIAP1-overexpressing (pTRIAP1) HCT116 cells were injected subcutaneously into the flank of nude mice and tumor growth was monitored by measuring tumor size at various times post injection." (PMID 36387192, 2022). "(C) Immunohistochemical analysis of TRIAP1, PCNA and CAV1 in isolated PC3 xenograft tumours." (PMID 30871022, 2019). "Either co-implantation with WPMY-1 cells, control or TRIAP1-transfected, did not change tumour growth." (PMID 30871022, 2019). "Therefore, the activation of TRIAP1 and suppression of LC3B might contribute to the tumor-promoting function of YY1 in CRC." (PMID 38769122, 2024). "Exploring whether miR-107 can be used as a tumor marker to distinguish GC, and secondly, the downstream signaling pathway of TRIAP1 has not been explored in depth, and this will also be the direction of our later research." (PMID 35480301, 2022).
TRIAP1 also shares sentences with these, for which no sentence is quoted: adenocarcinoma (1 paper); asthma (1); diabetes (1); liver disease (1); lung fibrosis (1); oral squamous cell carcinoma (1); pituitary adenomas (1); pituitary tumor (1); prostatic adenocarcinomas (1); radiation injury (1).